TSLP (thymic stromal lymphopoietin)
Diseases named in the same sentence as TSLP in open-access papers (continued):
Sharing a sentence is not in itself a finding about the gene and the disease.
breast carcinoma (continued). "Notably, the supplement of GM-CSF and TSLP completely rescue the proliferation and invasion of 4T1 or MDA-MB-231 cells, suggesting that arctigenin inhibits breast cancer cell proliferation and invasion via GM-CSF and TSLP." (PMID 32887217, 2020). "The TSLP signaling pathway interacts with other immune pathways and may promote survival of breast and pancreatic cancer cells, although its effects in breast cancer remain poorly understood." (PMID 32756008, 2020). "Malignant breast tumors exhibited higher TSLP expression than benign breast tumors." (PMID 31210014, 2019). "Finally, Soumelis and collaborators reported that TSLP was undetectable or expressed at low levels in breast cancer and in several human breast cancer cell lines." (PMID 30057581, 2018). "In another study, it was reported that breast cancer cells can produce TSLP." (PMID 30057581, 2018). "In contrast to increased TSLP expression reported in breast cancer and pancreatic cancer, we found that TSLP expression levels was significantly down-regulated in colon tumors by using two sets of public dataset and the surgical specimens we collected from patients of colon cancer." (PMID 26919238, 2016). "A recent study has shown that breast cancer cells have high expression levels of TSLP, indicating that the TSLP may be critical in the development of breast cancer." (PMID 25075970, 2014). "In conclusion, our study found that common variants in the SOCS4, TSLP and HGF genes might be related with breast cancer prognosis in Korean women." (PMID 25075970, 2014). "In this study, we found that the rs1952438 in the suppressors of cytokine signaling (SOCS4) gene, rs2289278 in the thymic stromal lymphopoietin (TSLP) gene and rs2074724 in the hepatocyte growth factor (HGF) gene were highly associated with a poor prognosis of breast cancer." (PMID 25075970, 2014). "In addition, survival analysis showed that VEGFD and TSLP could be used to predict the prognosis of patients with breast cancer." (PMID 35472078, 2022). "However, it is unclear whether TSLP induction can also block tumor growth in advanced, metastatic breast cancer models." (PMID 36467403, 2022). "Finally, we examined TSLP expression in normal mammary glands and breast cancers in humans." (PMID 35657353, 2022). "In addition to its essential role in polarization of TSLP-stimulated CD4+ T cells, we find that baseline IL-4/13 signaling, which is also implicated in normal mammary gland development, can protect against breast cancer development." (PMID 35657353, 2022). "Studies also showed TSLP enhances the lung metastasis of mammary tumour through an alveolar macrophage-dependent mechanism; and those induced by tumour-derived IL-1α in infiltrating myeloid cells can promote the survival of breast cancer cells and lung metastasis." (PMID 33652749, 2021). "In one model they crossed the MMTV-polyoma middle T (PyMttg) breast cancer-prone with the K14-TSLPtg mice (K14-TSLPtgPYMttg), whereas in the other model WT mice were topically treated with calcipotriol, which is known to induce TSLP expression in mouse keratinocytes." (PMID 33042121, 2020). "For example, IL1β positively modulates TSLP production and secretion in DCs in vitro, and in a recent study, myeloid cells, including neutrophils and monocytes, have been shown to produce TSLP in response to IL1α, a mechanism that was responsible for breast cancer spreading." (PMID 32285594, 2020). "The expression of β-catenin S33A, a frequently occurring site mutation of β-catenin in cancers, could partially rescue the proliferation and invasion of breast cancer cells treated with arctigenin, while GM-CSF and TSLP dual treatment could completely rescue the proliferation and invasion." (PMID 32887217, 2020). "Taken together, arctigenin could inhibit the expressions of GM-CSF and TSLP in breast cancer cells." (PMID 32887217, 2020).
breast carcinoma (continued). "Kuan and Ziegler demonstrated that TSLPR is expressed by human breast cancer cells and mouse TAM expressed TSLP." (PMID 40873585, 2025). "We have previously demonstrated that the induction of Thymic Stromal Lymphopoietin (TSLP) leads to a robust antitumor CD4+ T helper 2 (Th2) cell immunity that suppresses skin and breast cancer development." (PMID 35565302, 2022). "Interestingly, TSLP levels in terminal PyMttg TslprKO tumors were restored back to WT mammary gland levels, suggesting that TSLP loss in breast cancer is due to negative selection against this cytokine to escape TSLP-induced Th2 cell immunity during the early malignant transformation." (PMID 35657353, 2022). "To determine the mechanism by which TSLP-stimulated CD4+ T cells suppressed breast carcinogenesis, we examined spontaneous breast cancer development in K14-Tslptg, MMTV-PyMTtg (Tslp-PyMttg) mice compared with PyMttg controls on the BALB/c background." (PMID 35657353, 2022). "Then, both univariate and multivariate logistic regression analyses demonstrated that 6 genes regulated by the RUNX family had a significant relationship with the prognosis of breast cancer patients, including PSME2, ULBP2, IL18, TSLP, NPR3, and TRDV1." (PMID 36092942, 2022). "TSLP, as an epithelium-derived alarmin, induces a robust and tumor-specific CD4+ T cell immunity against breast cancer." (PMID 35657353, 2022). "Kaplan–Meier survival analysis and log-rank tests were used to determine the prognostic significance of expression of the three genes, VEGFD, TSLP, and PKMYT1, in patients with breast cancer." (PMID 35472078, 2022). "Accordingly, three consistently relevant genes (i.e., VEGFD, TSLP, and PKMYT1) were selected for the diagnosis of breast cancer." (PMID 35472078, 2022). "Decreased GM-CSF and TSLP resulted in the mute of STAT3/β-catenin signaling and the suppression of breast cancer progression." (PMID 32887217, 2020). "While, arctigenin decreased the expression of GM-CSF and TSLP and muted STAT3/β-catenin signaling in breast cancer cells, resulting in inhibited self-renewal ability of BCSCs." (PMID 32887217, 2020). "The present study supported that arctigenin suppressed breast cancer progression through the inhibition of GM-CSF, MMP-3, MMP-9, and TSLP." (PMID 32887217, 2020). "Thymic stromal lymphopoietin (TSLP) was abundantly expressed by several mouse and human breast cancer cell lines." (PMID 30597969, 2018). "Thus, calcipotriol and other agents that can induce TSLP will trigger CD4+ Th2 immunity for early and late breast cancer treatment." (PMID 39782693, 2025). "Collectively, these data reveal a negative selection against TSLP expression during early breast cancer development in humans, which can be reversed by TSLP induction to prevent and treat breast cancer." (PMID 35657353, 2022). "Previously, we have demonstrated that thymic stromal lymphopoietin (TSLP), an epithelium-derived cytokine and a master regulator of allergic inflammation in barrier organs, blocks breast cancer development through the activation of CD4+ T cells." (PMID 35657353, 2022). "Thus, a novel antitumor mechanism driven by TSLP-stimulated CD4+ T cells and delivered by TNF-α and IFN-γ cytokines results in the senescence of advanced breast cancer cells." (PMID 36467403, 2022). "In addition, we found positive correlations between TSLP expression and CSF2/IL3/IL5 and differentiation genes expression in human breast cancer." (PMID 35657353, 2022). "In addition, three stable relevant genes, namely VEGFD, TSLP, and PKMYT1, were chosen for the diagnosis of breast cancer." (PMID 35472078, 2022). "Furthermore, arctigenin-induced depletion of GM-CSF and TSLP inhibited STAT3 phosphorylation and β-catenin signaling resulting in decreased proliferation, invasion and stemness of breast cancer cells in vitro and in vivo." (PMID 32887217, 2020).
breast carcinoma (continued). "Numerous tumor-derived cytokines including granulocyte macrophage colony-stimulating factor (GM-CSF), thymic stromal lymphopoietin (TSLP), matrix metalloproteinase 3 (MMP-3) and matrix metalloproteinase 9 (MMP-9) have been reported to contribute to breast cancer progression." (PMID 32887217, 2020). "It has been shown that breast-cancer-derived TSLP, but not tumor-infiltrating fibroblasts, drives tumor-promoting inflammatory Th2 cells present in the malignant microenvironment." (PMID 30214685, 2018). "Consistent with the dominant role of CD4+ Th2 cells in mediating TSLP’s antitumor effects during early carcinogenesis, topical TSLP induction by calcipotriol treatment results in the induction of CD4+ Th2 cell immunity against late-stage breast cancer progression." (PMID 39782693, 2025). "Mechanistically, arctigenin decreased the promoter activities of GM-CSF and TSLP via hindering the nuclear translocation of NF-κB p65, and consequently, inhibited STAT3/β-catenin signaling, resulting in decreased proliferation, invasion and stemness of breast cancer cells in vitro and in vivo." (PMID 32887217, 2020). "However, one investigation claimed that no meaningful correlation has been identified between TSLP pathway activity and breast cancer." (PMID 32850805, 2020). "To investigate which, if any, of the three proteins secreted by the metastatic breast cancer cells (SLPI, TSLP, and G-CSF) have a functional role in tumor growth and metastasis, we next used lentivirally-transduced shRNA to stably inhibit translation of SLPI, TSLP, or G-CSF in 4T1 cells." (PMID 29312532, 2017). "Furthermore, the study using human breast cancer cell lines also indicate that TSLP signaling might not be a critical pathway in the progression of human breast cancer." (PMID 40787610, 2025). "Therefore, VEGFD and TSLP could be used to predict prognosis in patients with breast cancer, whereas PKMYT1 is not suitable for this purpose." (PMID 35472078, 2022). "Furthermore, arctigenin intervention suppressed protein expressions and mRNA level of GM-CSF, MMP-3, MMP-9 and TSLP in breast cancer cells, suggesting that arctigenin decreases the secreted GM-CSF, MMP-3, MMP-9 and TSLP at the transcriptional level in breast cancer cells." (PMID 32887217, 2020).
viral infection (41 papers, 2012 to 2026). "Pleiotropic cytokine TSLP is implicated in cancer development, chronic inflammation, fat metabolism, and viral infections such as SARSCoV-2 and influenza viruses, apart from their well-known role in type 2 inflammatory responses." (PMID 39057040, 2024). "We showed that the late addition of budesonide attenuates the increase in TSLP caused by viral infection." (PMID 32823491, 2020). "Viral infection or stimulation with dsRNA can upregulate TSLP expression, an effect that is further amplified in the presence of IL-4 or IL-13." (PMID 41576028, 2026). "One possible reason for this observation is that, in patients with severe ECRS, TSLP production is markedly increased in the paranasal sinus mucosa, where Th2 predominance is likely when combined with viral infection." (PMID 40937152, 2025). "TSLP is released from the airway epithelium in response to allergens, viral infection, and type 2 cytokines, and it activates dendritic cells and ILC2s to promote Th2 inflammation, positioning it upstream of the IgE, IL-5, and IL-13 pathways." (PMID 41487819, 2025). "Future studies aimed at determining the immune response pattern of long-form and short-form TSLP, as demonstrated in inflammatory diseases such as ulcerative colitis, particularly in viral infections, would be of scientific interest." (PMID 36851770, 2023). "The function of TSLP appears to be that of a master cytokine that has the potential to initiate an inflammatory cascade during a virus infection, leading to the cytokine storm observed during SARS-CoV-2 infection." (PMID 36851770, 2023). "It is known that viral infections increase the expression of airway epithelium-born cytokines such as IL-25, IL-33, and thymic stromal lymphopoietin (TSLP) and stimulate ILC2 responses." (PMID 36326393, 2022). "Following the local epithelial damage due to viral infection, production of IL-25, IL-33, and TSLP increases, which stimulates ILC2s, and as a result, T2 inflammation is induced." (PMID 36326393, 2022). "Recent studies indicate that viral infection can induce TSLP expression in upper airway microfold (M) cells, and that expression of TSLP correlates with viral load after influenza virus infection." (PMID 34659250, 2021). "In response to aeroallergens exposure, parasitic or viral infection, the bronchial epithelium releases the cytokines IL-25 and IL-33, and thymic stromal lymphopoietin (TSLP), which results in ILC2 activation." (PMID 33917396, 2021). "TSLP has protective activity under certain conditions and can prevent the development of cancer or enhance resistance to viral infections." (PMID 34659250, 2021). "Although TSLP is induced by viral infection of CD8+ T cells, there have been conflicting reports regarding its actions on CD8+ T cells during the primary response to influenza infection." (PMID 33439121, 2021). "Viral infection can induce epithelial cells to produce TSLP through activating the Toll-like receptor 3- interferon-related factor-3 pathway." (PMID 34131408, 2021). "Under an allergic environment, airway epithelial cells express thymic stromal lymphopoietin (TSLP) and IL-33 in response to viral infection and promote generation of TH2 cells." (PMID 32637363, 2020). "Recently, it has been reported that hMPV infection induces the production of thymic stromal lymphopoietin (TSLP) as an early response to the viral infection by AECs." (PMID 30405642, 2018). "TSLP can be induced in epidermal epithelial cells by a variety of stimuli including scratching, viral infections, inflammatory cytokines, protease allergens, bacteria and bacterial products." (PMID 27777593, 2016). "Viral infection with rhinovirus, human metapneumovirus and respiratory syncytial virus can induce TSLP expression in airway epithelial cells." (PMID 27826297, 2016). "In the microenvironment of small airway epithelial cells, particularly during viral infections, the presence of IL-4 or IL-13 may enhance the expression of TSLP and IL-8." (PMID 41576028, 2026).
viral infection (continued). "Within the microenvironment of small airway epithelial cells, particularly during viral infections, the presence of IL-4 or IL-13 may augment the expression of TSLP and IL-8." (PMID 41576028, 2026). "Furthermore, type I IFNs abundant during viral infections can increase both TSLP and TLR3 expression in the keratinocytes." (PMID 40007792, 2025). "Therefore, viral infection appears to be the primary inducer of TSLP production in paranasal sinus epithelial cells." (PMID 40937152, 2025). "Viral infections, such as those caused by rhinovirus, influenza virus, respiratory syncytial virus (RSV), and lymphocytic choriomeningitis virus, can also cause the synthesis of TSLP in the lungs." (PMID 39057040, 2024). "However, TSLP inhibited memory CD8+ T-cell responses to secondary viral infection with influenza or acute systemic LCMV infection." (PMID 33439121, 2021). "We also found that TSLP uniformly diminished the CD8+ T cell responses to secondary acute viral infection in all tissues examined in both pulmonary influenza infection and acute LCMV systemic infection, underscoring a greater effect for TSLP on secondary CD8+ T cell responses than primary responses." (PMID 33439121, 2021). "Overall, the effect of TSLP on CD8+ T cells during the effector phase of a primary acute infection may vary according to the viral infection and tissues analyzed, but our data support the potential for an inhibitory effect by TSLP." (PMID 33439121, 2021). "The IL-33 and TSLP pathways, may be a point of intersection where viral infections and allergic exposures combine to result in increased eosinophilic inflammation and a heightened risk of exacerbation from the activation of eosinophils." (PMID 31490928, 2019). "In conclusion, our data suggest that viral infection may contribute to maintaining and amplifying the T2 immune response commonly seen in CRSwNP, through the release of TSLP and IL-25 by epithelial cells of polyps." (PMID 28127565, 2016). "Our observation suggests that viral infections may enhance the T2 biased immunologic response of nasal polyps through the release of TSLP and IL-25 by epithelial cells." (PMID 28127565, 2016). "Therefore, more severe TSLP-Th2 exacerbating cycles may be initiated in patients with severe ECRS following viral infection." (PMID 40937152, 2025). "Indeed, viral infections may exacerbate Th2‐high inflammation by inducing epithelial cell‐derived cytokines such as IL‐25, IL‐33, and thymic stromal lymphopoietin (TSLP), which further activate and recruit type 2 helper T cells and eosinophils." (PMID 39466641, 2025). "Interestingly, a TSLP involvement in viral infection has been less investigated, although it is well established that its expression is elevated in respiratory syncytial virus-infected airway epithelial cells and plays a non-redundant role on anti-viral CD8 T cell responses." (PMID 33536486, 2021). "The TLR3 induced expression of TSLP introduces a mechanism by which the Th2-skewed tissue environment might arise in nasal polyps and invites a further evaluation of the potential contribution of current or past viral infections to polyposis pathogenesis." (PMID 27050744, 2016). "TSLP activates the ILC2 cells, which in turn drive the immune response towards Th2, further disrupting the skin's ability to defeat viral infections [60,69,]." (PMID 40007792, 2025). "Thymic stromal lymphopoietin (TSLP) levels are elevated in response to smoking, excessive β2 -agonist use, viral infections, and exposure to allergens such as house dust mite." (PMID 40492166, 2025). "Viral recognition receptors, such as toll-like receptor 3 (TLR3) expressed by epithelial cells, are activated to produce inflammatory cytokines and chemokines, including thymic stromal lymphopoietin (TSLP), CCL26, and CXCL8 when viral infection occurs." (PMID 32120846, 2020).